B4GALT7 (beta-1,4-galactosyltransferase 7)
Description:
Required for the biosynthesis of the tetrasaccharide linkage region of proteoglycans, especially for small proteoglycans in skin fibroblasts.
Synonyms: Beta4Gal-T7; XGALT1; XGALT-1; EDSP1; EDSSLA; EDSSPD1; XGPT; XGPT1
Tractability: Small molecule: a structure with a bound ligand is known. Antibody: UniProt predicts a signal peptide or a membrane-spanning region. PROTAC: ubiquitination databases record sites on it; its protein half-life has been measured.
Gene: Protein-coding gene on chromosome 5 (177,600,114 to 177,611,056, forward strand). Ensembl gene ENSG00000027847.
Subcellular location: Golgi apparatus, Golgi stack membrane
Pathways (Reactome):
Disease: Defective B4GALT7 causes EDS, progeroid type
Metabolism: Glycosaminoglycan-protein linkage region biosynthesis
Gene Ontology:
Molecular function: beta-N-acetylglucosaminylglycopeptide beta-1,4-galactosyltransferase activity; galactosyltransferase activity; manganese ion binding; protein binding; xylosylprotein 4-beta-galactosyltransferase activity; glycosyltransferase activity
Biological process: glycosaminoglycan biosynthetic process; negative regulation of fibroblast proliferation; protein N-linked glycosylation; proteoglycan metabolic process; supramolecular fiber organization; glycosaminoglycan-protein linkage region biosynthetic process; protein modification process; proteoglycan biosynthetic process; carbohydrate metabolic process
Cellular component: Golgi apparatus; membrane; Golgi membrane; Golgi cisterna membrane
Genetic constraint (gnomAD): Loss-of-function variants: 30 observed, 33.14 expected, observed/expected ratio (o/e) 0.91, 90% interval 0.68 to 1.23. The upper end of that interval is the gene's LOEUF score, 1.23, which puts it in group 5 of 6, group 1 being the genes least tolerant of losing a copy. Missense variants: 507 observed, 453.46 expected, observed/expected ratio (o/e) 1.12, 90% interval 1.04 to 1.2. Synonymous variants: 213 observed, 187.89 expected, observed/expected ratio (o/e) 1.13, 90% interval 1.01 to 1.27.
Gene-disease validity (ClinGen):
ClinGen rates the evidence that B4GALT7 causes each of these diseases.
Ehlers-Danlos syndrome, spondylodysplastic type, 1 (autosomal recessive): Definitive.
Homologues: Orthologues: chimpanzee B4GALT7 (100% identical), rabbit B4GALT7 (94% identical), dog B4GALT7 (94% identical), pig B4GALT7 (93% identical), rat B4galt7 (93% identical), mouse B4galt7 (92% identical), guinea pig B4GALT7 (76% identical), macaque B4GALT7 (76% identical), tropical clawed frog b4galt7 (73% identical), zebrafish b4galt7 (66% identical), Drosophila melanogaster beta4GalT7 (45% identical), Caenorhabditis elegans sqv-3 (39% identical). Paralogues in human: B4GALT2 (30% identical), B4GALT6 (30% identical), B4GALT3 (29% identical), B4GALT1 (29% identical), B4GALT5 (29% identical), B4GALT4 (27% identical).
Diseases named in the same sentence as B4GALT7 in open-access papers:
B4GALT7 is named in the same sentence as 24 diseases in open-access papers, as found by Europe PMC text mining. Sharing a sentence is not in itself a finding about the gene and the disease. The quoted sentences say what the papers report.
Ehlers-Danlos syndrome (9 papers, 2006 to 2025). The Ehlers–Danlos syndromes (EDS) are a clinically and genetically heterogeneous group of heritable connective tissue disorders (HCTDs) characterized by joint hypermobility, skin hyperextensibility, and tissue fragility. "We also identified a mutation in the glycosaminoglycan biosynthetic enzyme b4galt7 that represents a new zebrafish disease model for the progeroid form of Ehlers-Danlos Syndrome." (PMID 16759393, 2006). "Recessive mutations in B4GALT7 are directly linked to dwarfism in humans and Friesian horses, and have been associated with the short stature phenotype in spondylodysplastic Ehlers-Danlos syndrome." (PMID 35969758, 2022). "Compound heterozygous and homozygous mutations in B4GALT7, the enzyme that adds the first Gal residue to -serine-o-xyl- cause Ehlers-Danlos syndrome (EDS) spondylodysplastic type 1 which is characterized by short stature, muscle hypotonia and bowing of limbs." (PMID 35465334, 2022). "Mutations in B4GALT7 cause skeletal dysplasia, Ehlers-Danlos syndrome and Larson of Reunion Island syndrome (LRS), since B4GALT7 is correlated with the initiation of glycosaminoglycan side chain synthesis of PGs." (PMID 38025683, 2023). "B4GALT7 mutations are associated with a rare subtype of the Ehlers-Danlos syndrome (EDS), spondylodysplastic EDS (B4GALT7-spEDS; OMIM #130070), characterized by short stature, joint hypermobility, hyperelastic skin, osteopenia and ocular problems." (PMID 31196143, 2019).
spondylodysplastic EDS (7 papers, 2017 to 2021). "The two other forms of “spondylodysplastic EDS”, namely B3GALT6 deficiency and B4GALT7 deficiency, are also associated with short stature, but in those conditions, short stature can be explained by skeletal dysplasia." (PMID 32295219, 2020). "Defects in B4GALT7 and B3GALT6, encoding galactosyltransferases, lead to spondylodysplastic Ehlers-Danlos syndrome (spEDS)." (PMID 31438591, 2019). "Later, the EDS nosology has used the name “spondylodysplastic EDS” for a group of three conditions, B3GALT6 deficiency (better known as spondyloepimetaphyseal dysplasia with joint laxity, Beighton type), B4GALT7 deficiency, and SLC39A13 deficiency (the original spondylo-cheiro-dysplastic type)." (PMID 32295219, 2020).
dwarfism (6 papers, 2016 to 2025). "Numerous studies indicate that mutations in the B4GALT7 gene can lead to abnormal skeletal development, resulting in conditions such as short stature and dwarfism." (PMID 39596516, 2024). "A mutation in B4GALT7 has been associated with dwarfism and development of tendon laxity in Friesian horses." (PMID 37645058, 2023). "B4GALT7 is highly expressed in the growth plate, especially in the proliferative zone; mutations have been shown to cause dwarfism in livestock, e.g., horses." (PMID 35464367, 2022). "We suggest that the identified mutation of equine B4GALT7 leads to the typical dwarfism phenotype in Friesian horses due to deficient splicing of transcripts of the gene." (PMID 27793082, 2016). "Furthermore, mutations in B4GALT7 have been linked to dwarfism in Frisian horses, with the specific mutation B4GALT7(g." (PMID 39596516, 2024).
Ehlers-Danlos syndrome, progeroid type (2 papers, 2016 to 2024). "In humans, mutations in B4GALT7 cause the Ehlers-Danlos syndrome, progeroid type 1 (EDSP1, OMIM130070) and Larsen of Reunion Island syndrome (LRS)." (PMID 27793082, 2016). "Mutations in B4GALT7 in humans are associated with Ehlers-Danlos syndrome progeroid type 1 and Larsen of Reunion Island syndrome." (PMID 27793082, 2016).
glioma (2 papers, 2020 to 2021). A benign or malignant brain and spinal cord tumor that arises from glial cells (astrocytes, oligodendrocytes, ependymal cells). "In addition, there is no research on B4GALT7, CHST12, G6PC2 and TPBG in glioma." (PMID 33553434, 2021).
Intellectual disability (1 paper, 2019). "Mild to moderate intellectual disability is present in most individuals with mutations in B4GALT7 and all patients with mutations in XYLT1 suffer from a degree of intellectual disability." (PMID 31196143, 2019).
linkeropathies (1 paper, 2023). "To date, five genes, encoding various glycosyltransferases, have been linked to linkeropathies; besides the XYLT2 gene, there are the genes XYLT1 (OMIM * 608124), B4GALT7 (OMIM * 604327), B3GAT3 (OMIM * 606374), and B3GALT6 (MIM:* 615291)." (PMID 36833424, 2023).
lung carcinoma (1 paper, 2022). "Interestingly, Human sulfatase-2 (SULF2), an HS 6-O-endosulfatase involved in modulating HS biological activities, and B4GALT7 have been previously found to promote, respectively, carcinogenesis and progression in lung cancers." (PMID 36362413, 2022).
microstomia (1 paper, 2019). "Wide forehead, hypertelorism, and microstomia are more common in B4GALT7-spEDS, whereas frontal bossing, micrognathia, and abnormal dentition characterize B3GALT6- and SLC39A13-spEDS." (PMID 31438591, 2019).
progeroid syndrome (1 paper, 2020). A group of rare genetic disorders which mimic physiological aging, making affected individuals appear to be older than they are. "Two signaling paths identified in the secretomes of HFD-MSCs were related to senescence and aging phenomena: the sirtuin signaling pathway, and the defective B4GALT7 pathway associated with progeroid syndromes." (PMID 33361524, 2020).
tumor (4 papers, 2022 to 2025). "Highly expressed miR-338-3p suppressed HCC cell invasive abilities and rescued the tumor-promoting effect of B4GALT7 in HCC." (PMID 38025683, 2023). "B4GALT7 encodes galactosyltransferase I and it is highly expressed in HCC cells and human HCC tissues compared with para-tumor specimens." (PMID 38025683, 2023). "B4GALT7 was upregulated in HCC tissues compared to para-tumor specimens in three GEO datasets (GSE14520, GSE25097, GSE84402) (P < 0.001) and the TCGA database using the UALCAN portal (P < 0.001)." (PMID 38025683, 2023). "Collectively, these results suggested that miR-338-3p rescued the tumor-promoting effect of B4GALT7 in HCC." (PMID 38025683, 2023). "Consequently, these results demonstrated that highly expressed miR-338-3p rescued the tumor-promoting effect of B4GALT7 in HCC." (PMID 38025683, 2023). "B4GALT7 was overexpressed in seven (70%) HCC tissues compared with paired para-tumor specimens." (PMID 38025683, 2023). "B4GALT7 was highly expressed in a large number of cancer tissues compared to para-tumor specimens." (PMID 38025683, 2023). "The expression levels of B3GAT3, XYLT1, XYLT2, B4GALT7, and B3GALT6 were significantly upregulated in OS tissues compared to those in non-tumor tissues, according to the analysis of the bulk RNA-seq dataset (PRJNA539828)." (PMID 38690160, 2024). "Consistently, B4GALT7 was upregulated in HCC cell lines and tissues compared with corresponding para-tumor specimens." (PMID 38025683, 2023).
infection (3 papers, 2018 to 2024). The state of being infected such as from the introduction of a foreign agent such as serum, vaccine, antigenic substance or organism. "B4GALT7 knock out prevents the formation of heparan sulfate on the cell surface of HeLa cells, rendering them unsusceptible to RSV attachment and subsequent infection." (PMID 38543928, 2024).
cancer (2 papers, 2016 to 2023). A tumor composed of atypical neoplastic, often pleomorphic cells that invade other tissues. "In the cases of B4GALT6 and B4GALT7, no knowledge is available for their relevance to cancers." (PMID 27092876, 2016).
connective tissue disorder (2 papers, 2017 to 2022). A disease involving the connective tissue. "B4GALT7 is involved in glycosylation, has a role in connective-tissue disorders, and is related to disturbed fibril organization and proteoglycan synthesis." (PMID 35464367, 2022).
B4GALT7 also shares sentences with these, for which no sentence is quoted: Osteopenia (3 papers); skeletal dysplasia (2); colon adenocarcinoma (1); developmental delay (1); hepatocellular carcinoma (1); Larsen of Reunion Island syndrome (1); Larsen syndrome (1); melanoma (1); Platyspondyly (1); rectum adenocarcinoma (1).